IMMT (inner membrane mitochondrial protein)
Description:
Component of the MICOS complex, a large protein complex of the mitochondrial inner membrane that plays crucial roles in the maintenance of crista junctions, inner membrane architecture, and formation of contact sites to the outer membrane. Plays an important role in the maintenance of the MICOS complex stability and the mitochondrial cristae morphology.
Synonyms: HMP; MIC60; MINOS2; PIG4; PIG52; P87; P89; MICOS60; P87/89
Tractability: Antibody: UniProt predicts a signal peptide or a membrane-spanning region. PROTAC: ubiquitination databases record sites on it; its protein half-life has been measured.
Gene: Protein-coding gene on chromosome 2 (86,142,798 to 86,195,626, reverse strand). Ensembl gene ENSG00000132305.
Subcellular location: Mitochondrion inner membrane; Mitochondrion
Subcellular location (Human Protein Atlas): Mitochondria
Pathways (Reactome):
Organelle biogenesis and maintenance: Cristae formation
Gene Ontology:
Molecular function: protein binding; RNA binding
Biological process: cristae formation; inner mitochondrial membrane organization
Cellular component: membrane; MIB complex; MICOS complex; mitochondrial inner membrane; mitochondrion; SAM complex; mitochondrial crista junction; mitochondrial envelope; mitochondrial intermembrane space
Genetic constraint (gnomAD): Loss-of-function variants: 32 observed, 64.36 expected, observed/expected ratio (o/e) 0.5, 90% interval 0.37 to 0.67. The upper end of that interval is the gene's LOEUF score, 0.67, which puts it in group 2 of 6, group 1 being the genes least tolerant of losing a copy. Missense variants: 698 observed, 759.14 expected, observed/expected ratio (o/e) 0.92, 90% interval 0.86 to 0.98. Synonymous variants: 271 observed, 286.61 expected, observed/expected ratio (o/e) 0.95, 90% interval 0.86 to 1.05.
Homologues: Orthologues: chimpanzee IMMT (100% identical), macaque IMMT (98% identical), rabbit IMMT (93% identical), dog IMMT (92% identical), guinea pig IMMT (91% identical), pig IMMT (90% identical), mouse Immt (90% identical), rat Immt (86% identical), tropical clawed frog immt (66% identical), zebrafish immt (59% identical), Caenorhabditis elegans immt-1 (25% identical), Drosophila melanogaster Mitofilin (25% identical), and 1 more.
Diseases named in the same sentence as IMMT in open-access papers:
IMMT is named in the same sentence as 102 diseases in open-access papers, as found by Europe PMC text mining. Sharing a sentence is not in itself a finding about the gene and the disease. The quoted sentences say what the papers report.
breast carcinoma (10 papers, 2011 to 2024). "Recently, IMMT was identified as a promising biomarker for the diagnosis and prognosis of patients with breast cancer." (PMID 37240154, 2023). "This suggests that IMMT may play a role in the pathogenesis of HER-2 positive breast cancer, or there may be a certain correlation between IMMT and the HER-2 signaling pathway, and further research is needed to validate this hypothesis." (PMID 38834715, 2024). "In addition, low IMMT expression in breast cancer cells is involved in decreased mitochondrial activity, increased oxidative stress and suppressed cell cycle." (PMID 37240154, 2023). "The results showed that DYNLT1, IMMT, RAB2A, and SLC25A5 were unfavorable factors for breast cancer prognosis in the lipid metabolic pathway." (PMID 35919504, 2022). "Moreover, in the case of control samples, we found overexpression of the proteins: PRDX2, PRDX5 and AIFM1 involved in ROS; TUSC2 in PMM; ALKBH7, RHOT1, SAMM50, IMMT and HSPA9 in the MMO; and FUNDC2 in MIT compared to luminal A and basal-like breast cancer tumors." (PMID 35327574, 2022).
Parkinson disease (8 papers, 2018 to 2025). A progressive degenerative disorder of the central nervous system characterized by loss of dopamine producing neurons in the substantia nigra and the presence of Lewy bodies in the substantia nigra and locus coeruleus. "Heterozygous, missense mutations within the mitochondrial targeting sequence of IMMT were identified in a population of patients with either sporadic or familial Parkinson’s disease." (PMID 38467404, 2024). "Although there is little knowledge about the function of IMMT, alterations in this marker have been reported in association with different diseases, including Down syndrome, diabetic cardiomyopathy, and Parkinson's disease." (PMID 35919504, 2022).
prostate carcinoma (5 papers, 2018 to 2024). A carcinoma that arises from epithelial cells of the prostate gland. "IMMT has been reported as a requirement for tumor cell proliferation, including for osteosarcoma cells, prostate cancer cells, and BC cells." (PMID 36899366, 2023).
lung adenocarcinoma (4 papers, 2013 to 2024). A carcinoma that arises from the lung and is characterized by the presence of malignant glandular epithelial cells. "Based on the TCGA database, high IMMT mRNA expression is also associated with poorer prognosis of patients with lung adenocarcinoma." (PMID 31583841, 2019). "High IMMT expression is associated with poorer prognosis of patients with lung adenocarcinoma." (PMID 31583841, 2019). "To compare the present immunohistochemical data, we analyzed IMMT mRNA expression levels in lung adenocarcinoma patients using the TCGA database." (PMID 31583841, 2019). "Following IMMT‐knockdown with siRNA in A549 lung adenocarcinoma cells, we confirmed the role of the IMMT gene in tumor cell proliferation." (PMID 31583841, 2019). "Further, treating A549 cells derived from lung adenocarcinoma, with IMMT siRNA resulted in significantly decreased proliferation." (PMID 31583841, 2019). "The aims of this study were to examine IMMT expression in lung adenocarcinoma and evaluate its correlation with clinicopathological parameters and patient prognosis." (PMID 31583841, 2019). "IMMT expression was immunohistochemically studied in 176 consecutive lung adenocarcinoma resection tissues, and its correlations with clinicopathological parameters were evaluated." (PMID 31583841, 2019). "In lung adenocarcinomas, weakly to marked cytoplasmic granular staining of IMMT was detected to varying degrees." (PMID 31583841, 2019). "In summary, we report for the first time that IMMT expression is related to a more advanced stage of the disease, larger tumor size, and intratumoral vascular invasion in resected lung adenocarcinoma." (PMID 31583841, 2019). "Therefore, the aims of this study were to immunohistochemically examine IMMT expression in surgically‐resected lung adenocarcinoma and analyze its correlation with clinicopathological parameters and patient prognosis." (PMID 31583841, 2019). "In the present study, we first confirmed that IMMT expression correlates with several clinicopathological parameters and poorer prognosis and is an independent prognostic factor for survival in patients with resected lung adenocarcinoma." (PMID 31583841, 2019). "Further studies are required to elucidate the biological function of IMMT in lung adenocarcinoma." (PMID 31583841, 2019).
gastric cancer (2 papers, 2022 to 2025). A primary or metastatic malignant neoplasm involving the stomach. "Recently, a study has revealed the prognostic value of IMMT protein in gastric cancer." (PMID 35931981, 2022).
ischemia (2 papers, 2023). A hypoperfusion of the BLOOD through an organ or tissue caused by a PATHOLOGIC CONSTRICTION or obstruction of its BLOOD VESSELS, or an absence of BLOOD CIRCULATION. "Down-regulation of IMMT has been reported to be involved in local inflammation in kidneys with ischemia-reperfusion injuries." (PMID 37240154, 2023).
ovarian carcinoma (2 papers, 2020 to 2022). A malignant neoplasm originating from the surface ovarian epithelium. "Our result reveals multiple candidate protein biomarkers, including SAMM50 and IMMT, to be causally associated with response to treatment in ovarian cancer." (PMID 35931981, 2022). "Similarly, in this study, IMMT expression was decreased in cis-resistant cell line as compared to its sensitive cell line, suggesting its usefulness as biomarker for platinum resistance in ovarian cancer." (PMID 33053689, 2020).
Arthritis (1 paper, 2019). Inflammation of a joint. "However, the SDN map identified five cSABPs (ENO1, FTL, IMMT, PDCD6IP and HSPA6) that were associated with various types of arthritis." (PMID 31511554, 2019).
invasive breast carcinoma (1 paper, 2023). A carcinoma that infiltrates the breast parenchyma. "DYNLT1, IMMT, RAB2A, and SLC25A5 are independent prognostic factors for invasive breast carcinoma and confer a poor prognosis 2)." (PMID 37179822, 2023).
cancer (37 papers, 2012 to 2025). A tumor composed of atypical neoplastic, often pleomorphic cells that invade other tissues. "Among these genes, we observed a large number of cancer‐related genes, such as ACTB (encoding β‐actin), IMMT (encoding inner membrane mitochondrial protein), and PFDNs (encoding Prefoldin)." (PMID 41312091, 2025). "This study demonstrated the differential expression of IMMT in human cancers." (PMID 38834715, 2024). "However, research on the significance of IMMT in cancers is rare, and the only literature proposed that IMMT expression might be related to cancer prognosis." (PMID 38834715, 2024).
tumor (24 papers, 2013 to 2026). "Due to the pivotal role of IMMT in regulating the redox status, we investigated its association with mitochondrial antioxidant defenses in BC tumor samples." (PMID 36899366, 2023). "Third, the possible mechanism underlying the tumor-promoting role of IMMT was identified by functional enrichment modules and confirmed by experimental verification." (PMID 36899366, 2023). "Mechanistically, IMMT loss promotes ATF6α-ATF6β heterodimer formation, whereby ATF6α stabilizes ATF6β protein, enabling ATF6β to engage PPARγ through direct physical interaction and orchestrate redox homeostasis remodeling that sustains tumor cell proliferation." (PMID 42049712, 2026). "Analysis of clinical information revealed that IMMT upregulation was correlated with tumor size (> 2 cm), Ki-67 expression (> 15%), and advanced histological grade." (PMID 38834715, 2024). "The immunohistochemistry staining data of the Human Protein Atlas confirmed an overexpressed IMMT protein in BC tumor tissue compared to normal tissue." (PMID 36899366, 2023). "IMMT-knockout cells exhibit dysregulated mitochondrial functions, leading to an arrested cell cycle, reduced cell proliferation, suppressed tumor growth, and increased apoptosis." (PMID 36899366, 2023). "The single-cell RNA-seq based on GSE75688 then showed that IMMT was predominantly expressed in tumor cells, although was relatively low in T cells." (PMID 36899366, 2023). "Low expressions of IMMT in tumor predicted dismal prognosis in KIRC patients and correlated with KIRC progression." (PMID 37240154, 2023). "Cell type deconvolution using single-cell data from the GSE111360 dataset showed that the expression of IMMT was evenly distributed across various immune cells in the tumor microenvironment." (PMID 37240154, 2023). "As a key regulatory subunit of mitochondria, mitochondrial inner membrane protein (IMMT), plays a vital role in degenerative diseases, but its role in tumor is almost unknown." (PMID 38834715, 2024). "Additionally, IMMT regulates the biological behavior of tumor cells by modulating the dynamic processes of mitochondrion division, fusion, transportation, degradation, and biogenesis." (PMID 38834715, 2024). "Interestingly, the BC tumor was more abundant in gene signatures of mitophagy, in which IMMT acts as a key regulator." (PMID 36899366, 2023). "Indeed, RNA expression level and protein abundance of both SAMM50 and IMMT in the same tumor samples showed poor correlation (cor < 0.25)." (PMID 35931981, 2022). "In the TCGA datasets, BC tumor tissue showed elevated gene expression levels of IMMT, CHCHD6, CHCHD3, APOO, and MICOS10 as compared to normal tissue, while the APOOL level was decreased in tumor tissue as compared to normal tissue." (PMID 36899366, 2023). "We found that DYNLT1, IMMT, RAB2A, and SLC25A5 were tumor biomarkers to assess the prognosis of BRCA patients, and all of them were high-risk genes, and the parameters indicated that 4 genes would make the prognosis of BRCA poorer." (PMID 35919504, 2022). "However, IMMT might be involved in the aggressive nature of this tumor type." (PMID 31583841, 2019). "Furthermore, low IMMT expressions are correlated with KIRC progression, indicating a potential role for IMMT in tumor development." (PMID 37240154, 2023). "Furthermore, IMMT expression and other clinicopathological variables including p‐TNM stage, tumor differentiation, vascular invasion, lymphatic invasion, pleural invasion, and adjuvant chemotherapy were entered into multivariate analysis using the Cox‐proportional hazards regression model." (PMID 31583841, 2019).
infection (11 papers, 2016 to 2025). The state of being infected such as from the introduction of a foreign agent such as serum, vaccine, antigenic substance or organism. "Subsequently, combined with ubiquitinome MS screening, we identified a mitochondrial substrate IMMT, which is ubiquitylated by BipD-mediated modification, was essential for induction of host cell mitophagy responsive to the infection of B. pseudomallei." (PMID 38834545, 2024). "Consistently, loss of either CUL3 or IMMT reduced the colocalization of mitochondria with lysosome upon B. pseudomallei WT infection, while no obvious differences were found when infected with ΔbipD mutant." (PMID 38834545, 2024). "On the other hand, we could verify the infection-dependent interaction of Mic60/IMMT with SneRING." (PMID 41196921, 2025). "Interestingly, Mic60/IMMT, CKAP4, and Erlin2 were primarily present in the pull-downs of Sne-infected samples expressing FLAG-tagged SneRING, indicating that active infection is necessary for the interactions with SneRING to take place." (PMID 41196921, 2025). "Of note, we found a discontinuous fluorescence signal of TOMM20 and the colocalization of Ub and IMMT in response to B. pseudomallei infection, indicating that outer mitochondrial membrane (OMM) severing may contribute to a possibility for IMMT exposure and ubiquitination following infection." (PMID 38834545, 2024).
adenocarcinoma (1 paper, 2019). A common cancer characterized by the presence of malignant glandular cells. "Based on 176 patients with adenocarcinoma, multivariate analysis revealed that IMMT expression was an independent predictor of poorer survival (HR, 1.99; 95% confidence interval [CI], 1.06–3.74; P = 0.031)." (PMID 31583841, 2019). "In the present study, IMMT expression was significantly correlated with vascular invasion and a poorer prognosis in patients with adenocarcinoma." (PMID 31583841, 2019). "High‐IMMT expression was observed in 84 of 176 (47.4%) adenocarcinomas." (PMID 31583841, 2019).
infectious disease (1 paper, 2023). A disorder directly resulting from the presence and activity of a microbial, viral, or parasitic agent in humans.
IMMT also shares sentences with these, for which no sentence is quoted: diabetes (6 papers); adenoma (3); amyotrophic lateral sclerosis (3); degenerative diseases (3); diabetic cardiomyopathy (3); glioma (3); lung carcinoma (3); microvillus inclusion disease (3); Obesity (3); pancreatic cancer (3); Barrett esophagus (2); cardiac hypertrophy (2); Down syndrome (2); glaucoma (2); glioblastoma (2); kidney cancer (2); neurological disease (2); optic atrophy (2); osteosarcoma (2); Salmonella Infections (2); Acidosis (1); age (1); alcoholic liver diseases (1); asthma (1); Atrophy (1); autosomal dominant optic atrophy (1); bacterial infection (1); bile duct cancer (1); bone osteosarcoma (1); breast (1).
A further 58 diseases each share a sentence with IMMT in 1 paper.